RNU6-47P (RNA, U6 small nuclear 47, pseudogene)
Synonyms: RNU6-47
Gene: Small nuclear RNA gene on chromosome 5 (109,014,834 to 109,014,940, reverse strand). Ensembl gene ENSG00000206593.
Homologues: Orthologues: chimpanzee U6 (97% identical), rat U6 (93% identical), mouse Gm26056 (88% identical), pig U6 (86% identical), guinea pig U6 (83% identical), rabbit U6 (78% identical). Paralogues in human: RNU6-33P (96% identical), RNU6-1 (95% identical), RNU6-116P (95% identical), RNU6-15P (95% identical), RNU6-2 (95% identical), RNU6-3P (95% identical), RNU6-4P (95% identical), RNU6-5P (95% identical), RNU6-6P (95% identical), RNU6-9 (95% identical), RNU6-10P (94% identical), RNU6-12P (94% identical), and 1286 more.